OR51B5 (olfactory receptor family 51 subfamily B member 5)
Description:
Odorant receptor.
Synonyms: HOR5'Beta5; OR11-37
Tractability: Antibody: its Gene Ontology location is reachable by antibodies, with high confidence; UniProt places it where antibodies can reach, with medium confidence; UniProt predicts a signal peptide or a membrane-spanning region.
Gene: Protein-coding gene on chromosome 11 (5,303,444 to 5,505,652, reverse strand). Ensembl gene ENSG00000167355.
Subcellular location: Cell membrane
Pathways (Reactome):
Sensory Perception: Expression and translocation of olfactory receptors; Olfactory Signaling Pathway
Gene Ontology:
Molecular function: olfactory receptor activity; G protein-coupled receptor activity; signaling receptor activity
Biological process: sensory perception of smell; cellular response to lipid; detection of chemical stimulus involved in sensory perception of smell; G protein-coupled receptor signaling pathway; system process
Cellular component: membrane; plasma membrane
Genetic constraint (gnomAD): Loss-of-function variants: 0 observed, 0.22 expected, observed/expected ratio (o/e) 0, 90% interval 0 to 1.88. That is too few expected variants to judge how well the gene tolerates losing a copy. Missense variants: 426 observed, 363.71 expected, observed/expected ratio (o/e) 1.17, 90% interval 1.08 to 1.27. Synonymous variants: 169 observed, 135.5 expected, observed/expected ratio (o/e) 1.25, 90% interval 1.1 to 1.42.
Homologues: Orthologues: macaque OR51B5 (91% identical), pig OR51B5 (79% identical). Paralogues in human: OR51B6 (70% identical), OR51B2 (66% identical), OR51B4 (63% identical), OR51G2 (54% identical), OR51G1 (52% identical), OR51V1 (51% identical), OR51L1 (51% identical), OR51A7 (48% identical), OR51I2 (48% identical), OR51A4 (47% identical), OR52K2 (47% identical), OR51F2 (47% identical), and 39 more.
Diseases named in the same sentence as OR51B5 in open-access papers:
OR51B5 is named in the same sentence as 9 diseases in open-access papers, as found by Europe PMC text mining. Sharing a sentence is not in itself a finding about the gene and the disease. The quoted sentences say what the papers report.
acute myelogenous leukemia (1 paper, 2016). "In the present study, we detected the expression of OR51B5 in the chronic myelogenous leukemia (CML) cell line K562 and in white blood cell samples of clinically diagnosed acute myelogenous leukemia (AML) patients by reverse transcription-PCR and immunocytochemical staining." (PMID 27551504, 2016).
asthma (1 paper, 2024). "Thus, the study underscores the potential utility of targeting lung epithelial OR51B5 and OR1G1 as drug targets for odorant-induced asthma with non-type 2 inflammation." (PMID 39538061, 2024).
esophageal cancer (1 paper, 2025). A primary or metastatic malignant neoplasm involving the esophagus. "Our study provides an alternative workflow for discovering critical regulatory sites for control tumorigenesis, and reveals a novel OR51B5 triggering mechanism underlying esophageal cancer progression." (PMID 40523880, 2025). "In this study, we successfully established a comprehensive workflow (CiFR) to identify the OR51B5 locus served as a critical chromatin site contributing to esophageal cancer progression, and revealed that OR51B5 is a novel esophageal cancer suppressor." (PMID 40523880, 2025). "Here, we developed a comprehensive workflow to identify potential functional olfactory receptor family 51 subfamily B member 5 (OR51B5) and demonstrated that OR51B5 locus acted as a key spatial element contributing to the progression of esophageal cancer." (PMID 40523880, 2025). "We observed that OR51B5 overexpression enhances intracellular Ca2+ signaling, reduces N-Ras expression, and inhibited the growth and metastasis of esophageal cancer." (PMID 40523880, 2025). "In this study, we successfully established a CiFR workflow and identified the OR51B5 served as novel tumor suppressor in esophageal cancer progression." (PMID 40523880, 2025). "We further found that CTCF-EZH2 contributes to the repressive chromatin status on the OR51B5 promoter and impaired the entry of RNA polymerase II, subsequently inactivating OR51B5 to activate N-Ras expression and promote the growth and metastasis of esophageal cancer." (PMID 40523880, 2025).
esophageal tumor (1 paper, 2025). "Further analysis revealed that OR51B5 was low expressed in esophageal tumor tissues." (PMID 40523880, 2025).
leukemia (1 paper, 2024). A malignant (clonal) hematologic disorder, involving hematopoietic stem cells and characterized by the presence of primitive or atypical myeloid or lymphoid cells in the bone marrow and the blood. "OR51B5 and OR1G1 have been previously found in various cell types; for example, OR51B5 in keratinocytes, K562 leukemia cells, while OR1G1 was detected in Dermal papilla cells (DPCs) and primary iliac Enterochromaffin cells." (PMID 39538061, 2024).
tumor (3 papers, 2020 to 2025). "Subsequently we demonstrated that closed chromatin impaired the entry of RNA polymerase II and inhibited the transcription of OR51B5, thereby causing N-Ras activation and promoting tumor cell proliferation and metastasis." (PMID 40523880, 2025). "In this paper, however, we for the first time show that OR51B5 acts as a tumor suppressor in ESCC and is significantly associated with survival in ESCC patients." (PMID 40523880, 2025). "Additionally, we observed that N-Ras protein levels in human esophageal epithelial cell were slightly higher than those in tumor variant lines expressing ectopic OR51B5 (lanes 2–3)." (PMID 40523880, 2025). "Next, we measured the expression of OR51B5 in tumor cells using real-time PCR and western blot assay." (PMID 40523880, 2025). "To examine the tumor growth and migration capability after OR51B5 overexpression in vivo, we establish metastatic models in nude mice." (PMID 40523880, 2025). "The proliferation of tumor cells was significantly reduced after overexpression of OR51B5 compared to the control (oeCtrl) group (square)." (PMID 40523880, 2025). "Among them, OR51B5 was significantly down-regulated in tumor tissues compared to normal tissues (with fold changes >2)." (PMID 40523880, 2025). "In the OR51B5-overexpressing groups, we found that both tumor weight (n = 5, P < 0.0001) and volume (n = 6, P < 0.0001) were significantly reduced compared with the control group." (PMID 40523880, 2025). "The protein expression of FCRL1, GRIK2, MAPK12, and OR51B5 showed differential level between normal colon tissue and tumor tissue." (PMID 38144182, 2023). "Conversely, OR51B5 expression was found to be low in tumor samples and high in normal tissues." (PMID 40523880, 2025). "To determine whether OR51B5 could alter tumor behavior, we overexpressed OR51B5 in ESCC cells." (PMID 40523880, 2025).
OR51B5 also shares sentences with these, for which no sentence is quoted: myelogenous leukaemia (2 papers); chronic myelogenous leukemia (1); prostate carcinoma (1).